ENSG00000261611 (novel transcript)
Gene: Protein-coding gene on chromosome 16 (71,447,600 to 71,489,311, reverse strand). Ensembl gene ENSG00000261611.
Genetic constraint (gnomAD): Missense variants: 95 observed, 112.89 expected, observed/expected ratio (o/e) 0.84, 90% interval 0.71 to 1. Synonymous variants: 38 observed, 40.34 expected, observed/expected ratio (o/e) 0.94, 90% interval 0.73 to 1.24.